ZG16B (zymogen granule protein 16B)
Description:
Functions as a lectin that binds to selective commensal dental plaque bacteria, such as Streptococcus vestibularis. Contributes to maintain homeostasis in the oral microbiome by capturing commensal microbes and regulating their growth using a mucin-assisted clearance mechanism. Plays an important role in pancreatic tumor progression and metastasis. Promotes pancreatic cancer cells migration and invasion through the TLR4/MyD88/NF-kappaB signaling pathway, without the involvement of the TLR4/TRIF pathway.
Synonyms: PAUF; HRPE773; PRO1567; JCLN2; EECP
Tractability: Antibody: UniProt places it where antibodies can reach, with high confidence; its Gene Ontology location is reachable by antibodies, with high confidence; UniProt predicts a signal peptide or a membrane-spanning region.
Gene: Protein-coding gene on chromosome 16 (2,830,162 to 2,839,585, forward strand). Ensembl gene ENSG00000162078.
Subcellular location: Secreted; Cytoplasm; Cell membrane; Apicolateral cell membrane
Subcellular location (Human Protein Atlas): Vesicles; Nucleoplasm; Predicted to be secreted
Gene Ontology:
Molecular function: protein binding; proteoglycan binding
Biological process: cell migration; defense response to bacterium; positive regulation of angiogenesis; positive regulation of vascular permeability
Cellular component: apicolateral plasma membrane; cytoplasm; extracellular exosome; extracellular region; plasma membrane
Genetic constraint (gnomAD): Loss-of-function variants: 8 observed, 7.27 expected, observed/expected ratio (o/e) 1.1, 90% interval 0.64 to 1.8. That is too few expected variants to judge how well the gene tolerates losing a copy. Missense variants: 232 observed, 218.55 expected, observed/expected ratio (o/e) 1.06, 90% interval 0.95 to 1.18. Synonymous variants: 92 observed, 87.56 expected, observed/expected ratio (o/e) 1.05, 90% interval 0.89 to 1.25.
Homologues: Orthologues: chimpanzee ZG16B (99% identical), mouse Sbpl (29% identical).
Diseases named in the same sentence as ZG16B in open-access papers:
ZG16B is named in the same sentence as 24 diseases in open-access papers, as found by Europe PMC text mining. Sharing a sentence is not in itself a finding about the gene and the disease. The quoted sentences say what the papers report.
pancreatic cancer (16 papers, 2015 to 2024). "Pancreatic adenocarcinoma upregulated factor (PAUF), also known as ZG16b, has been extensively investigated as a tumorigenic factor and diagnostic marker in pancreatic cancer as well as gastric, colon, ovarian, oral squamous cell, and cervical carcinoma." (PMID 33731895, 2021). "With 3D confocal images, we also observed dual-staining of these cells for combinations of macrophage markers (CD204 or CD206) and pancreatic cancer markers ZG16B or S100PBP." (PMID 28957348, 2017). "Furthermore, ZG16B enhances angiogenesis and vascular permeability and then promotes tumor progression and metastasis of pancreatic cancer by stimulating CXCR4 expression and FAK activation." (PMID 33336077, 2021). "Additionally, ZG16B helps pancreatic cancer cells to resist oncolytic parvovirus H-1 infection via IFNAR-mediated signaling." (PMID 33336077, 2021). "ZG16B has been researched as a biomarker for the diagnosis and progression of many tumors, including pancreatic cancer and colon cancer, but its detailed biological function is also unknown." (PMID 34957219, 2021). "As a special factor in pancreatic cancer, ZG16B promotes activation and maturation of DCs through TLR4 signaling pathway to mediate immune system activation; meanwhile, it could also increase and activate MDSCs to benefit tumor formation, showing a double-sided effect on the immunotherapy." (PMID 33336077, 2021). "ZG16B as a biomarker of pancreatic cancer, ovarian cancer, etc. has no research correlated to breast cancer yet." (PMID 33336077, 2021). "Pancreatic adenocarcinoma upregulated factor (PAUF; also known as ZG16B) is a novel tumor-promoting secreted protein that plays a critical role in metastasis and cancer progression in several types of cancer, such as pancreatic cancer, cervical cancer, colorectal cancer, and ovarian cancer." (PMID 39518973, 2024).
pancreatic adenocarcinoma (14 papers, 2011 to 2024). "Zymogen granule protein 16B(ZG16B), also identified as Pancreatic adenocarcinoma upregulated factor, is a paralog of ZG16A which has a 65.5% of similarity and 36% identity, first found to be overexpressed in pancreatic ductal adenocarcinoma." (PMID 33336077, 2021).
breast carcinoma (4 papers, 2020 to 2023). "Zymogen granule protein 16B (ZG16B) has been identified in various cancers, while so far the association between ZG16B and breast cancer hasn’t been explored." (PMID 33336077, 2021). "Other selected genes, SLC40A1, ADAMTS15, THSD4, GREB1, and SLC44A4 have been reported to be related to breast cancer, and ZG16B, FDCSP, and SRARP have been associated with other types of tumors." (PMID 32795265, 2020). "Moreover, ZG16B was closely associated with foregone biomarkers and crucial factors in breast cancer." (PMID 33336077, 2021). "The upregulation of ZG16B (Zymogen granule protein 16B) expression correlates to a better prognosis of breast cancer patients; however, ZG16B promotes colorectal cancer progression through the Wnt-β-catenin pathway." (PMID 38203246, 2023). "Our work demonstrates the latent capacity of ZG16B to be a biomarker for prognosis of breast cancer." (PMID 33336077, 2021). "Since it showed that ZG16B indeed upregulated in breast cancer, in order to expound the expression pattern of ZG16B in breast cancer, Ualcan analysis was conducted to compare the expression level of ZG16B in different clinical indicators." (PMID 33336077, 2021). "These demonstrate that ZG16B has strong interactions with various proteins involved in breast cancer formation, indicating the special role of ZG16B in breast cancer from another point of view." (PMID 33336077, 2021). "We further examined the impact of ZG16B on the prognosis of distinct molecular types of breast cancer by Kaplan–Meier plotter using the RFS as an indicator." (PMID 33336077, 2021). "The pooled meta-analysis confirmed that the mRNA upregulation of ZG16B was extremely significant in breast cancer (p = 5.97 × 10−4)." (PMID 33336077, 2021). "In this report, we found that ZG16B expressed highly in breast cancer, and depth analysis was conducted further to clarify the possible effect of ZG16B in breast cancer through public medical databases." (PMID 33336077, 2021). "Persuasive testament was presented explaining the connection between the overexpression of ZG16B and breast cancer." (PMID 33336077, 2021). "STRING analysis was performed to extrapolate the possible mechanism of ZG16B action in breast cancer and find the interaction between ZG16B and other proteins." (PMID 33336077, 2021). "In order to obtain more detailed information at genetic level, we have detected the co-expression genes of ZG16B in breast cancer through Oncomine database." (PMID 33336077, 2021). "Expression levels in different conditions, possible mechanisms of action and the effect of prognosis of ZG16B in breast cancer were presented, demonstrating its potential value to be a biomarker for breast cancer in clinical practice." (PMID 33336077, 2021). "Patients with PR-positive breast cancer had the most favorable prognosis among breast cancer subtypes with ZG16B high expression, suggesting its special role in PR-positive breast cancer." (PMID 33336077, 2021). "In this study, Oncomine, Cancer Cell Line Encyclopedia (CCLE), Ualcan, and STRING database analyses were conducted to detect the expression level of ZG16B in breast cancer with different types." (PMID 33336077, 2021). "Interestingly, higher expression of ZG16B represented a longer RFS for all breast cancer patients (HR = 0.77, p = 0.00095)." (PMID 33336077, 2021). "We found that ZG16B was significantly upregulated in breast cancer." (PMID 33336077, 2021). "In addition, the mechanism of demethylation epigenetic factor has been represented by Ualcan to explain the upregulation of ZG16B in breast cancer." (PMID 33336077, 2021). "Furthermore, ZG16B has correlations with various biomarkers and factors of breast cancer, some of which have precisely inhibitory effect on breast cancer." (PMID 33336077, 2021). "In conclusion, ZG16B upregulates in breast cancer and represents a favorable prognosis in patients." (PMID 33336077, 2021).
breast carcinoma (continued). "ZG16B has been detected as a biomarker in various malignant tumors; however, the association between ZG16B and breast cancer has not been noticed yet." (PMID 33336077, 2021). "Furthermore, in order to verify the high-level expression signal of ZG16B in breast cancer, we used CCLE analysis to detect the transcription level of ZG16B in multiple cancer cell lines." (PMID 33336077, 2021).
colorectal cancer (4 papers, 2016 to 2024). A primary or metastatic malignant neoplasm that affects the colon or rectum. "For example, ZG16B, known to involve in metastasis in colorectal cancer, is potentially affected by rs9925556, and lower expression level of ZG16B that is correlated with shorter BCR-free survival in PCa." (PMID 27409348, 2016).
ovarian carcinoma (4 papers, 2018 to 2024). A malignant neoplasm originating from the surface ovarian epithelium. "Moreover, ZG16B can also have effect and be a biomarker for early diagnosis and prognosis of prostate cancer, oral squamous cell carcinoma, and especially ovarian cancer." (PMID 33336077, 2021).
asthma (1 paper, 2020). "Indirectly perturbed genes near ATF3 and EGR2 in the network include C2, SERPING1, ZG16B, and CEACAM3, all of which have been linked to immune response, asthma, or auto-immune diseases." (PMID 33095769, 2020).
atherosclerosis (1 paper, 2024). A disease characterized by the build-up of fatty material and calcium deposition in the arterial wall resulting in partial or complete occlusion of the arterial lumen. "Recent studies have found an upregulation of ZG16B in various cancers and it plays a significant role in the development of diseases such as atherosclerosis." (PMID 38566986, 2024).
breast tumor (1 paper, 2021). "Unsurprisingly, by the way of Ualcan, we found that the promoter methylation level of ZG16B significantly downregulated in primary breast tumor compared with that in normal tissues." (PMID 33336077, 2021).
Hyperglycemia (1 paper, 2021). An increased concentration of glucose in the blood. "It is tempting to suggest that the secretory function of salivary glands under hyperglycemia will be affected, and thus, ZG16B, as a secreted protein, will inevitably be affected and its expression reduced." (PMID 34957219, 2021).
influenza (1 paper, 2024). An acute viral infection of the respiratory tract, occurring in isolated cases, in epidemics, or in pandemics; it is caused by serologically different strains of viruses (influenzaviruses) designated A, B, and C, has a 3-day incubation period, and usually lasts for 3 to 10 days. "Although an association with SARS-CoV-2 has not been previously reported, ZG16B has been linked to anti-influenza activity in saliva and may interfere with viral interaction with cell-surface receptors through its carbohydrate-binding properties." (PMID 38007005, 2024).
periodontitis (1 paper, 2025). An acute or chronic inflammatory process that affects the tissues that surround and support the teeth. "This includes proteins such as ZG16B and carbonic anhydrase 1, whose relationship with periodontitis remains unclear." (PMID 40384977, 2025). "However, the function of ZG16B and its potential relationship with periodontitis remain unclear." (PMID 40384977, 2025).
prostate carcinoma (1 paper, 2022). A carcinoma that arises from epithelial cells of the prostate gland. "lncRNA LINC01082, miRNA hsa-miR-133a-3p, and genes TTLL12, PTGDS, GAS6, CYP27A1, PKP3, and ZG16B are the top RNAs having the potential to predict prognosis for prostate cancer." (PMID 35075375, 2022). "Finally, survival analysis, biological function analysis, and literature researched identified 8 key biomarkers (lncRNA LINC01082, miRNA hsa-miR-133a-3p, mRNA TTLL12, PTGDS, GAS6, CYP27A1, PKP3, and ZG16B) to predict prostate cancer prognosis." (PMID 35075375, 2022). "Moreover, ZG16B was found as a potential predictor of prostate cancer biochemical recurrence." (PMID 35075375, 2022). "The most interesting 8 prognostic biomarkers for prostate cancer included lncRNA LINC01082, miRNA hsa-miR-133a-3p, and genes TTLL12, PTGDS, GAS6, CYP27A1, PKP3, and ZG16B." (PMID 35075375, 2022). "We constructed ceRNA networks in the prostate cancer microenvironment and identified lncRNA LINC01082, miRNA hsa-miR-133a-3p, and genes TTLL12, PTGDS, GAS6, CYP27A1, PKP3, and ZG16B as the potential biomarkers to predict prognosis for prostate cancer." (PMID 35075375, 2022).
tumor (12 papers, 2015 to 2025). "ZG16B can regulate the Wnt/β-catenin pathway and enhance the immunosuppressive activity of myeloid-derived suppressor cells in the tumor microenvironment." (PMID 35075375, 2022). "Exploration of the expression network indicated that inflammatory genes (CXCL8, CXCL3, PIGR, and RNASE1) and Wnt pathway genes (GAST, REG1A, TFF3, and ZG16B) are upregulated in tumor stem cells of UGICs." (PMID 35646860, 2022).
cancer (10 papers, 2017 to 2024). A tumor composed of atypical neoplastic, often pleomorphic cells that invade other tissues. "Oncomine database was used to analyze the different expression levels of ZG16A and ZG16B between multiple types of cancer and the corresponding normal tissues." (PMID 33336077, 2021). "The results demonstrated that the transcription level of ZG16B was the highest among all types of cancer cell lines." (PMID 33336077, 2021). "Among all kinds of cancers, it was significant that the expression of ZG16B was upregulated in 7 analyses of 3 datasets from Curtis’, Finak’s, and TCGA database which met the threshold." (PMID 33336077, 2021).
ZG16B also shares sentences with these, for which no sentence is quoted: pancreatic ductal adenocarcinoma (3 papers); adenocarcinoma (2); cervical cancer (2); colon cancer (1); endometrial cancer (1); epithelial ovarian cancer (1); gastrointestinal carcinomas (1); infection (1); multiple sclerosis (1); oral disease (1).